EIF4E (eukaryotic translation initiation factor 4E)
Diseases named in the same sentence as EIF4E in open-access papers (continued):
Sharing a sentence is not in itself a finding about the gene and the disease.
infection (continued). "Therefore, the findings of the present study suggest that eIF4E/eIF(iso)4E plays important roles in the PStV infection cycle and may serve as a novel method for increasing the PStV resistance in economically important peanut cultivars." (PMID 28344571, 2017). "Because eIF4A is required for MNV1 translation, the role of eIF4E recruitment to VPg could be to ensure optimal helicase activity and unwinding of the structured 5′ region of the MNV1 genome, whereas the role of a potential interaction between p-eIF4E and VPg during infection is under investigation." (PMID 25561727, 2015). "Thus, it appears that MNV1 may induce eIF4E phosphorylation to maintain cell proliferation during infection or to control the translation of specific mRNAs involved in the antiviral response." (PMID 25561727, 2015). "Controlling eIF4E phosphorylation could therefore be a more general mechanism that RNA viruses use to modulate translation during infection and control the host response to infection." (PMID 25561727, 2015). "Moreover, using polysomal profile analysis, we show that phosphorylated eIF4E relocates to the polysomes during infection, and we provide evidence that this could induce the translational control of a subset of mRNAs during infection." (PMID 25561727, 2015). "Indeed, whereas the amount of polysomes decreased during infection to 75%, which could represent a drop in overall translation, we observed an accumulation of phosphorylated eIF4E in polysomes." (PMID 25561727, 2015). "Therefore, eIF4E/eIF(iso)4E may not only participate in the infection and translation of viruses, but it may also affect virus movement." (PMID 23505421, 2013). "Notably, eIF4E phosphorylation increased after ASFV infection of Vero cells." (PMID 19714237, 2009). "At late stages of infection, the ASFV protein pA224L induces the expression of eIF4G1 and eIF4E subunits of the eIF4F complex." (PMID 39123713, 2024). "Early in infection, an ASFV ubiquitin-conjugating enzyme (I215L) binds to eIF4E, inducing its overexpression, and to cullin 4B (CUL4B), which regulates mTOR activity." (PMID 37631977, 2023). "At late times of infection, the IAP homolog ASFV protein A224L induces the expression of eIF4G1 and eIF4E subunits of the eIF4F complex." (PMID 37631977, 2023). "To study the effects of DHT mediated by ZIP9 on the expression of PSD95 and the phosphorylation of ERK1/2 and eIF4E in HT22 cells, we constructed ZIP9 knockdown or overexpression HT22 stable cell lines by lentivirus infection." (PMID 37305050, 2023). "The relative mRNA expression levels of Mx1 and TOP1 were significantly upregulated, whereas those of eIF4E, G6PD and PGAM1 were significantly downregulated in PK-15 cells during infection with SVA." (PMID 35632606, 2022). "However, at the later stages of infection, when discontinuous transcription leads to the synthesis of multiple viral mRNAs bearing short sub-genomic 5′UTRs that strongly depend on eIF4E availability, cap-dependent initiation might become necessary for viral proliferation." (PMID 35849342, 2022). "After silencing 4EBP1 in MCF-7/ADR cells, the expression of eIF4E and MRP1 increased, and the resistance of MCF-7/ADR cells to Adriamycin after Ad-VT infection increased." (PMID 34869595, 2021). "The results showed that when the infection dose was an MOI of 10, rSG10-K1756A induced higher levels of eIF4E phosphorylation at 18 and 24 hpi than rSG10-G1780A and rSG10, accompanied by an increase in viral protein synthesis." (PMID 34585949, 2021). "In addition, HC-Pro from three potyviruses, including potato virus A (PVA), PVY, and TEV could interact with the eukaryotic translation initiation factors (eIF4E) and eIF(iso)4E of Nicotiana tabacum and eIF(iso)4E and eIF4E of potato suggesting possible new role(s) in potyvirus infection cycle." (PMID 34696360, 2021).
infection (continued). "A similar eIF4E recognition motif in PVA helper-component proteinase (HCPro) has been demonstrated to bind eIF4E/(iso)4E and to be essential for PVA infection." (PMID 32053987, 2020). "Up-regulation of eIF4e and other elongation initiation factors were only observed in the early event of DENV infection at/before 24-hour post-infection." (PMID 29404200, 2018). "The results showed that the level of endogenous p-eIF4E was increased upon PEDV, HSV-1, and PRV (lanes 1–2) infection." (PMID 30388805, 2018). "Cells were harvested at 12 h post-infection and lysates processed for Western blot analysis using antibodies to WNV NS3 protein, CHIKV capsid and total eIF4E." (PMID 27763553, 2016). "Infections with herpes simplex virus (HSV-1) and human cytomegalovirus both lead to an accumulation of phosphorylated eIF4E, whereas influenza virus, poliovirus, and encephalomyocarditis virus induce eIF4E dephosphorylation (reviewed in Ref." (PMID 25561727, 2015). "It was found that, during infection with herpes simplex virus (HSV), the viral gene product ICP0 promotes degradation of 4EBP-1 via proteasome, avoiding interaction with eIF4E." (PMID 25690796, 2015). "During ASFV infection, eIF4G and eIF4E are phosphorylated (Ser1108 and Ser209, respectively), whereas 4E-BP1 is hyperphosphorylated at early times post infection and hypophosphorylated after 18 h." (PMID 19714237, 2009). "However, eIF4E phosphorylation was increased at 16 h after infection and moderately decreased by ceranib-2 at 16 h and by SKI-II at 24 h after infection." (PMID 35370781, 2022). "The expression of total eIF4E was not affected by the infection or inhibitor treatment (evaluation not shown)." (PMID 35370781, 2022). "However, the expression of eIF4E was significantly decreased after infection with Ad-VT, and the level of MRP1 significantly increased after eIF4E overexpression and infection of the cells with Ad-VT." (PMID 34869595, 2021). "Treatment with okadaic acid, a potent phosphatase inhibitor, restored phosphorylation of MNK1/2 and eIF4E regardless of infection." (PMID 33014898, 2020). "Treatment with okadaic acid restored phosphorylation of MNK1/2 and eIF4E regardless of infection by T. gondii." (PMID 33014898, 2020). "It is possible that the lack of functionality of the eIF4F complex during infection leads to eIF4E inactivation." (PMID 29419763, 2018). "By detection with Western blot analysis using specific antibodies, components of the eIF4F complex, including eIF4E, eIF4A and PABP, were indifferently identified in both mock- and DENV2-infected cells after pull-down with m7GTP, especially in cells with DENV2 infection for 24 h." (PMID 28930151, 2017). "Whereas there was no obvious change in the level of eIF4E during infection, the level of p-eIF4E increased." (PMID 25561727, 2015). "Furthermore, infection with HIV-1 promotes the binding of DEAD-box helicase to eIF4G and PABP, so that eIF4E is displaced and the genome of this virus can be efficiently translated." (PMID 25690796, 2015). "When mutated Arabidopsis thaliana eIF4E and eIF(iso)4E were tested for susceptibility to Clover yellow vein virus (ClYVV) and Turnip mosaic virus (TuMV), eIF4E was shown to be necessary for infection by ClYVV but not for TuMV, while eIF(iso)4E was in contrast." (PMID 23505421, 2013). "Not only that, but also, it is interesting to note that eIF4E as well as eIF4GI were redistributed in ASFV-infected cells to localize within viral replicative sites at 8 hpi, while at late times of the infection, these factors were displaced to the periphery of viral factories." (PMID 19714237, 2009). "Notably, in some of the eIF4E-silenced cells, several small structures appeared upon ASFV-infection, possibly corresponding to aberrant viral factories, which did not react with p72 antibodies." (PMID 19714237, 2009). "Unlike eIF4G and PABPC1, eIF4E protein levels remained unchanged upon EV-D68 infection." (PMID 40294010, 2025).
infection (continued). "However, ZAP-C16 granules that formed after infection of A549 cells with MVA+C16 did not co-localize with poly(A) binding protein (PABP) nor with translation factors eIF4E nor eIF4G." (PMID 32866210, 2020). "In the early stages of infection, VACV induces surface integrin-β1-mediated PI3K activation, leading to hyperphosphorylation of 4EBP1 and the subsequent release of cap-binding protein eIF4E, which consequently augments the formation of the eIF4F complex enhancing VACV protein synthesis." (PMID 32455727, 2020). "We identify a key translation initiation factor with which the MTE interacts (eIF4E) and show how the MTE base pairs to the 5′ UTR to facilitate cap-independent translation, and that the functional MTE and the long-distance interaction are required for infection of maize." (PMID 32847851, 2020). "Strikingly, V5-4E-BP1 overexpression (i.e. reduced eIF4E/4E-BP1 ratio) prevented the asTORi-mediated increase of HSV1-dICP0 protein synthesis in transformed cells (4T1 and NT2196), and resulted in greater repression of HSV1-dICP0 infection by asTORi in normal cells (NMuMG)." (PMID 30138450, 2018). "We found that eIF4E phosphorylation occurs in iRapKO conditions at 12 hpi as previously reported and is independent of infection status; but phosphorylation of eIF4E in iRapKO cells did not compensate for the lack of mTORC1 signaling to promote CHIKV protein production in our studies." (PMID 27763553, 2016). "On the contrary, eIF4E knockouts prevent infection by ClYVV, but not by TuMV." (PMID 23443165, 2013). "Furthermore, HIV-1 and ΔVifVprX infections did not perturb the total protein levels of eIF4E and 4E-BP1." (PMID 22457629, 2012). "This could relate to the fact that hPIV3 infection also induces low levels of eIF4E and S6 phosphorylation in the absence of EGF stimulation." (PMID 19806178, 2009). "We report that either hPIV3 infection or transient expression of hPIV3-C both increase cellular response to EGF, as assessed by Elk1 transactivation and phosphorylation levels of ERK1/2, 40S ribosomal subunit protein S6 and translation initiation factor 4E (eIF4E)." (PMID 19806178, 2009). "Unexpectedly, when the infection dose was changed from an MOI of 10 to 0.01, rSG10-K1756A exhibited very weak proliferation that was independent of the eIF4E phosphorylation level." (PMID 34585949, 2021). "Unlike infection with live parasites, treatment of BMDM cultures with soluble T. gondii antigens (STAg) failed to inhibit eIF4E phosphorylation." (PMID 33014898, 2020). "Examination of other translation initiation factors such as eIF4E, eIF4A and eIF4G shows that MDV1 infection does not affect their accumulation or cellular distribution." (PMID 25503397, 2014). "The involvement of eIF4E in the viral infectious cycle appears to be restricted to potyviruses, as infection by TSWV, AMV, CMV and TMV is not impaired in transgenic lines silenced for eIF4E or eIF(iso)4E." (PMID 22242134, 2011). "Furthermore, stable infection with lenti-UCA1-siRNA inhibited the expression of AKT3, p-AKT3, p-mTOR, and S6K, and increased the expression of EIF4E in BGC-823 cells, when compared with blank and negative control cells." (PMID 29212166, 2017). "There was no modulation observable due to either RSVA2 or RV2 infection compared to untreated controls (lane 5 vs lane 1) or even poly(I:C) stimulation (lane 2 vs lane 1 at 1h; lane 6 vs lane 5 at 4 h), suggesting that translation of IFN genes in AECs is not dependent on phosphorylation of eIF4E." (PMID 31319869, 2019).
adenocarcinoma (4 papers, 2016 to 2024). A common cancer characterized by the presence of malignant glandular cells. "In other tumors, expression of eIF4E was reported to be more marked in neoplastic lesions than in preneoplastic lesions (e.g., higher expression of eIF4E in adenocarcinoma than in adenomatous polyps in the colon 26 or in infiltrating carcinoma compared with benign tumors of the head and neck 29)." (PMID 27440383, 2016).
hematologic cancers (3 papers, 2014 to 2023). "Most of the MNK inhibitors used in this type of hematological cancer also block eIF4E phosphorylation, as it happens in others." (PMID 32340135, 2020). "Given the critical function of XPO1 in controlling these crucial proteins, it is not unexpected that an elevation in XPO1 and eIF4E expression is frequently linked to an unfavorable prognosis in both solid and hematologic cancers." (PMID 37047788, 2023).
hematological malignancies (3 papers, 2018 to 2023). "The role of MNKs in the development and progression of solid tumors and hematological malignancies has been widely discussed, particularly in the context of cap dependent translation, regulated by phosphorylation of eIF4E." (PMID 34660602, 2021). "Knocking down eIF4E ameliorated tumorigenesis as well, and consequently, drugs targeting eIF4E to inhibit mRNA translation have been heavily tested in clinical trials for hematologic malignancies." (PMID 36711035, 2023).
neurodevelopmental disorder (3 papers, 2018 to 2025). A behavioral and cognitive disorder with onset during the developmental period that involves impaired or aberrant development of intellectual, motor, or social functions. "Downregulation of Mknk2 can impair eIF4E phosphorylation, leading to translational repression and disrupted protein synthesis, a mechanism increasingly implicated in neurodevelopmental disorders such as RTT." (PMID 41009596, 2025).
benign tumors (2 papers, 2016 to 2023). "EIF4E gene copy number is increased in invasive carcinomas compared to normal tissues and benign tumors." (PMID 37601696, 2023).
brain disease (2 papers, 2021 to 2022). "Disorders within the mTOR and MAPK pathways are characteristic of patients with ASD (e.g., an increase in protein p-EIF4E, rpS6, ERK1–2 in blood) and are an important target in the search for a treatment for this brain disease." (PMID 34579089, 2021).
head and neck tumor (2 papers, 2014 to 2021). "Previous studies have confirmed that there is an overexpression of eIF4E in head and neck tumor including of NPC, and eIF4E can enhance NPC cell proliferation and cell cycle progression." (PMID 24551240, 2014).
lung (2 papers, 2016 to 2022). "P-4EBP1 proteins in lung SCC and ADC tissues were significantly upregulated, as well as p-eIF4E protein (both P < 0.001)." (PMID 35737644, 2022). "Positive percentage of both p-Mnk1 and p-eIF4E expression was significantly higher in lung SCC and ADC tissues compared to the Non-CLT (P < 0.001)." (PMID 27050281, 2016).
CNS tumor (1 paper, 2018). "Interestingly, eIF4E over-expression has been established in other CNS malignancies such as GBM, while ribavirin treatment of GBM cells has been shown to decrease phosphorylation of eIF4E, suggesting a potential target in CNS tumor cells." (PMID 29487714, 2018).
colon (1 paper, 2018). "Emerging evidence suggests that hyperphosphorylation of 4E-BPs leading to enhanced eIF4E activity is linked to malignant progression in breast, ovarian, prostate and colon cancers." (PMID 30397197, 2018).
neurodegenerative disease (1 paper, 2025). A disorder of the central nervous system characterized by gradual and progressive loss of neural tissue and neurologic function. "Elongation initiation factor 4E (eIF4E) has been found exclusively in the tears of AD patients, suggesting its potential to differentiate between various neurodegenerative diseases." (PMID 40177250, 2025).
peripheral neuropathy (1 paper, 2021). A disorder affecting the peripheral nervous system. "This indicates that eIF4E affects pain perception associated with paclitaxel-induced peripheral neuropathy." (PMID 33912169, 2021). "We hypothesized that eIF4E phosphorylation regulates activation of specific macrophage and T-cell subpopulations, alters nociceptor metabolism, and glial activation during the early phase of paclitaxel-induced peripheral neuropathy." (PMID 33912169, 2021). "In this study, we used wild type and eIF4E-mutant mice of both sexes to investigate the role of cap-dependent translation and the contribution of immune cells and nociceptors in the periphery and glia in the spinal cord during paclitaxel-induced peripheral neuropathy." (PMID 33912169, 2021).
EIF4E also shares sentences with these, for which no sentence is quoted: acute lymphoblastic leukemia (4 papers); angiosarcoma (3); colon adenocarcinoma (3); Insulin resistance (2); lung fibrosis (2); memory impairment (2); neurological disorders (2); non-Hodgkin lymphoma (2); ovarian tumor (2); penile squamous cell carcinoma (2); pituitary adenomas (2); ACTHomas (1); acute myocardial infarction (1); alcohol (1); anaplastic astrocytoma (1); astrocytic tumor (1); atherosclerosis (1); autoimmune disease (1); Autoimmunity (1); bacterial infection (1); bone cancer (1); brain cancer (1); brain tumors (1); breast adenocarcinoma (1); Cachexia (1); cardiomyopathy (1); cervical squamous cell carcinoma (1); cholangiocarcinoma (1); chronic lung allograft dysfunction (1); chronic lymphocytic leukaemia (1).
A further 33 diseases each share a sentence with EIF4E in 1 paper.